MIR493 (microRNA 493)
Synonyms: hsa-mir-493; MIRN493; mir-493
Gene: MicroRNA gene on chromosome 14 (100,869,060 to 100,869,148, forward strand). Ensembl gene ENSG00000207989.
Gene Ontology:
Biological process: cellular response to estrogen stimulus; cellular response to leukemia inhibitory factor
Homologues: Orthologues: chimpanzee MIR493 (100% identical).
Diseases named in the same sentence as MIR493 in open-access papers:
MIR493 is named in the same sentence as 5 diseases in open-access papers, as found by Europe PMC text mining. Sharing a sentence is not in itself a finding about the gene and the disease. The quoted sentences say what the papers report.
glioma (1 paper, 2017). A benign or malignant brain and spinal cord tumor that arises from glial cells (astrocytes, oligodendrocytes, ependymal cells). "Overexpression of the E2F1 and its impact on cancer progression have recently been associated with miRNA deregulation in different types of cancer: melanoma, lung cancer, glioma and CRC, where marked reduction in expression was observed for MIR205, MIR493, MIR329 and MIR362, respectively." (PMID 28704519, 2017).
prostate carcinoma (1 paper, 2022). A carcinoma that arises from epithelial cells of the prostate gland. "Although one independent study has demonstrated the anti-tumor activity of MIR493 in prostate cancer via upregulation of N6-methyladenosine levels, another study revealed that MIR493 stimulates AKT signaling to enhance prostate cancer proliferation." (PMID 35317831, 2022). "MIR493 upregulates PHLPP2 (PH domain and leucine rich repeat protein phosphatase 2) to promote expression of BECN1 and ATG7, resulting in autophagy and reduced ability of prostate cancer cells in colony formation." (PMID 35317831, 2022).
MIR493 also shares sentences with these, for which no sentence is quoted: cancer (1 paper); lung carcinoma (1); melanoma (1).